FGF21 (fibroblast growth factor 21)
Diseases named in the same sentence as FGF21 in open-access papers (continued):
Sharing a sentence is not in itself a finding about the gene and the disease.
tumor (continued). "When the transplanted cells were cultured with 25 mM d-glucose, the inhibitory effect of p-FGF21 on the tumor was more obvious." (PMID 33753729, 2021). "These genes are involved in diverse cellular processes, including immunity (NCF4), regulation of glucose (FGF21), and a potential tumor suppressor (MCC)." (PMID 32531199, 2020). "We first compared the protein expression levels of FGF21 and FGFRs between normal and tumor tissues." (PMID 31408968, 2019). "Whereas the lost expression of FGF21 is found in high-grade HCC foci area of poorly differentiated tumor cells." (PMID 29184085, 2017). "Most interestingly, the FGF21 concentrations decreased significantly after removing the tumor and correlated positively with the levels of insulin and proinsulin." (PMID 28225059, 2017). "In contrast, FGFR1, the partner of KLB activated by FGF21, is widely expressed in adipocytes, normal luminal epithelium and tumor cells (orange staining)." (PMID 24279986, 2013). "Moreover, tumor cells secrete cytokines such as FGF21 to promote cholesterol biosynthesis in CD8+ T cells, contributing to their dysfunction." (PMID 41542770, 2026). "We hypothesized that FGF21 suppresses invasion and metastasis by modulating the tumor microenvironment—a key driver of PDAC progression." (PMID 41426308, 2025). "By contrast, the ICI-specific durable response might have been impacted by tumour immunosuppressive effects mediated by elevated FGF21 levels." (PMID 40242310, 2025). "ZFP36L1 targets mRNAs involved in tumor progression, such as FGF21, ZEB2, and Cyclin D." (PMID 41285712, 2025). "These include the role of GLP-1R in regulating fibroblast growth factor 21 (FGF21) synthesis, which has been implicated in cancer biology, as well as its anti-inflammatory effects, which could suppress tumor-promoting inflammation." (PMID 39777709, 2025). "Additionally, serum Fibroblast Growth Factor (FGF) 21 levels were found to positively correlate with post-DST cortisol, cortisol-to-ACTH ratio, and tumor size, suggesting a potential role for FGF21 as a biomarker of the cortisol secretion severity." (PMID 41007734, 2025). "•Tumour-secreted FGF21 functions as a secreted immune-checkpoint factor." (PMID 40242310, 2025). "Interestingly, compared to adjacent adipose tissues, tumor tissues in the SFD group showed minimal expression of FGF21, but there was a marked increase in the HFD group, as confirmed by western blot analysis." (PMID 38238320, 2024). "The hepatic FGF21 can reach tumor tissues via the circulating system." (PMID 38238320, 2024). "Importantly, we observed that FGF21 treatment over a period of 3 weeks significantly accelerated E0771 tumor growth, as evidenced by increased tumor volume and wet weight." (PMID 38238320, 2024). "FGF21 is expressed in hepatocytes both in non-tumor and tumor tissue." (PMID 37770545, 2023). "But whether the decreased FGF21 levels in tumor tissues were due to the decreased circulating FGF21 needs to be confirmed." (PMID 36263162, 2022). "It is noteworthy that targeting FGFR signaling reduced the pro-tumor effects of FGF21 on PTC cells." (PMID 36077709, 2022). "However, in a low-protein ketogenic diet, FGF21 knockout mice showed a comparable decrease in tumor growth to that of the wild type 87." (PMID 36263162, 2022). "In addition, under both high- or low-glucose conditions 19 days after transplantation, the mice injected with p-FGF21 cells had smaller tumor volumes than the mice implanted with p-N1 cells." (PMID 33753729, 2021).
tumor (continued). "Nonetheless, we may hypothesise the activation of a cellular cascade in which an increase in FGF21 level enhances the autophagic occurrence, which may play an anti-metastatic role, thus triggering an impediment to tumour progression." (PMID 32423132, 2020). "While expression of Dddit4, FGF21, and Nupr1 was decreased in tumor compared to non-tumor tissue." (PMID 32363190, 2020). "However, the role of FGF21 in proliferation and metastasis of the tumor in extrahepatic tissue is still poorly understood." (PMID 32570721, 2020). "In our studies, the serum levels of FGF21 were correlated with the clinical stage of the tumor." (PMID 32570721, 2020). "We investigated whether the involvement of FGF21 in tumor progression occurred via upregulation of EMT signaling and FGFR signaling." (PMID 31408968, 2019). "One year after tumor removal led to normalization of FGF21 and the other metabolic abnormalities." (PMID 30959789, 2019). "Tumor removal led to the normalization of FGF21 and the other metabolic abnormalities." (PMID 30959789, 2019). "Our findings indicated that high serum levels of FGF21 were significantly associated with recurrence-free survival and overall survival of patients with PTC, which suggested that FGF21 could serve as a new biomarker for predicting tumor progression." (PMID 31408968, 2019). "However, the exact role of FGF21 in tumor aggressiveness in extrahepatic tissue remains poorly understood." (PMID 31408968, 2019). "The effects of FGF21 in our study may have been induced by the upregulation of FGFR signaling, which suggests that FGF21 may induce growth-stimulating effects in tumor cells in a manner dependent on the expression of FGFRs and KLB." (PMID 31408968, 2019). "Other hypothesis, which deserves further investigation, is that the growing tumor induces FGF21-mediated insulin secretion which leads to an increased uptake of glucose by the tumor to sustain its energy requirements and growth." (PMID 27358750, 2016). "The metabolic reprogramming of breast epithelial cells caused by these changes contributes to the suppression of tumor progression, suggesting that the tumor-delaying effect of FGFR4 deficiency may be largely attributed to the elevated anti-obesogenic FGF21 and its resultant metabolic effects." (PMID 41328353, 2026). "Finally, we conducted a gene network analysis of the DEFA gene and found that there were tumor-suppressor-related genes associated with DEFA, including FGF21 and ITLN1, as well as tumor-promoting genes associated with DEFA, including GNB3, CRB2, DIO3, HPD, and Dll3." (PMID 41009818, 2025). "This suggests that FGF21 may contribute to tumor growth within the tumor microenvironment." (PMID 41262444, 2025). "Hence, FGF21 may be a new biomarker for predicting tumor progression, and targeting FGFR may be a novel therapy for the treatment of obese patients with PTC." (PMID 31408968, 2019). "Furthermore, successful tumor removal significantly decreased FGF21 levels." (PMID 30959789, 2019). "Additionally, elevated serum FGF21 was significantly related to aggressive tumor phenotypes." (PMID 31408968, 2019). "We hypothesized that KLb plays a role as a tumor promoter, together with FGF21 or FGF19." (PMID 29731962, 2018). "FGF21 suppresses the PI3K/AKT/mTOR/70S6K pathway, demonstrating that downregulation of this axis stimulates autophagy to restrict tumor growth and enhance apoptosis." (PMID 40740483, 2025). "Adiponectin has been shown to inhibit tumor cell proliferation through activation of the AMPK–PPARα signaling pathway, IL-10 suppresses proinflammatory cytokine expression, and FGF21 plays a role in modulating oxidative stress and immune homeostasis." (PMID 40731020, 2025). "The results showed that despite the presence of severe NAFLD status, FGF21 knockout diminished HFD-induced breast cancer tumor growth, resulting in comparable tumor volume and weight to the SFD group." (PMID 38238320, 2024).
tumor (continued). "The PPI network analysis with cancer-related terms defined six proteins: TGFBR2, TGF-alpha, FGF21, SMAD4, TGFBR1, and FZD3, most of which are involved in tumor development." (PMID 35999337, 2022). "Furthermore, tumor markers such as FGF21 and EPCAM are lowered following UGCG OE, which could be related to glucosylceramide (GlcCer) and lactosylceramide (LacCer) accumulation in glycosphingolipid-enriched microdomains (GEMs) and subsequently altered signaling protein phosphorylation." (PMID 34626204, 2021). "None of the selected proteins retained statistical significance in the main validation analysis, but two proteins of particular interest, FGF-21 and PPY, were identified when stratifying analyses by tumor location, stage and time to diagnosis." (PMID 33664295, 2021). "In detail, FGF1 and FGF10 were downregulated in most of the tumor types whereas FGF3, FGF5, FGF11, FGF19, FGF20, and FGF21 were upregulated in most of the tumor types." (PMID 32596330, 2020). "The aim of our study was to evaluate the changes of circulating levels of FGF21 and its relationship to energy and glucose metabolism in PPGL, before and one year after tumor removal." (PMID 30959789, 2019). "Previous study on human hepatic tissues demonstrates a high level of FGF21 expression in low-grade HCC foci area of well-differentiated cells, and also in tumor-adjacent and phenotypically normal liver area." (PMID 29184085, 2017). "This was in marked contrast to the gradually diminished or lost expression of FGF21 in the HCC foci areas with grade 2 of moderately-differentiated and grade 3 of poorly differentiated tumor cells." (PMID 23590285, 2013). "Hepatokines, particularly fibroblast growth factor 21 (FGF21), emerge as key mediators of tumor progression and potential biomarkers of metabolic vulnerability, while Fetuin-A and angiopoietin-like protein 8 (ANGPTL8) further support the liver's endocrine role in oncogenic signaling." (PMID 42278446, 2026). "Notably, acetoacetate displayed unique roles in cancer cells, including the promotion of tumor growth in BRAF-V600E+ cancer cells through the activation of MEK-ERK signaling and induction of FGF21 expression in HepG2 cells." (PMID 39554048, 2025). "For example, FGF21, which inhibits CD8 T cells by boosting cholesterol metabolism, was upregulated in BALF and may herald blunting of the anti-tumor responses." (PMID 40356899, 2025). "These transcriptomic data suggest that FGF21 exerts its effects, at least in part, by suppressing the Notch signaling pathway, a key regulator of inflammation and tumor progression." (PMID 41426308, 2025). "The cervical region contains not only superficial subcutaneous fat but also metabolically active brown adipose tissue, which may influence systemic inflammation and the tumor microenvironment (TME) via secretion of adiponectin, IL-10, and FGF21." (PMID 40731020, 2025). "Our central premise posits that therapeutic supplementation of FGF21 could potentially mitigate the invasive and metastatic progression of PDAC through modulation of the tumor microenvironment." (PMID 41426308, 2025). "The non-tumour portion of Atf4Δhep livers showed elevated cyclin-D1 (CCND1), mouse double minute 2 homologue (MDM2), connective tissue growth factor (CTGF), and DR5 mRNAs, but reduced FGF21 mRNA." (PMID 36996941, 2023). "Phosphorylation of FRS2α, ERK, and AKT, downstream events of FGF21 action, was markedly increased in both non-tumorous and tumorous parts of the liver of Atg7ΔHepFgf21+/+ mice and was abrogated in the liver of Atg7ΔHepFgf21−/− mice." (PMID 35321438, 2022). "Upregulated expression of various canonical FGFs (including FGF1, FGF2, and FGF 6–9) derived from tumor cells or stromal cells induces tumor progression in various cancers; however, the effects of circulating hormone-like FGFs (such as FGF19, FGF21, and FGF23) on tumors are unclear." (PMID 31408968, 2019).
tumor (continued). "Recombinant FGF21 led to tumor aggressiveness via activation of the FGFR signaling axis and epithelial-to-mesenchymal transition (EMT) signaling in PTC cells, and AZD4547, an FGFR tyrosine kinase inhibitor, attenuated the effects of FGF21." (PMID 31408968, 2019). "Previous studies have demonstrated that FGF21 is not required for ketogenesis induced by ketogenic diets and is independent of the tumor-suppressing effects of the ketogenic diet." (PMID 29443873, 2018). "Worth to note, CNAs of 37 genes were exclusively found in G3 tumours such as WNT7B (4 gains), BAD (3 gains), WEGFB (3 gains) and HDAC2 (3 losses) in respect to 65 CNA genes exclusively presented in G1 tumours, such as GRB2 (5 losses) and FGF21, STAT3, CTNNA3 and DVL3 with 3 losses each." (PMID 28486536, 2017). "However, we cannot preclude additional paracrine factors also contributing to tumor formation since transcripts for other secreted growth regulators (SOST, BMP7, BMP8A, WNT5B, WNT10B, and FGF21) exhibited increased abundance in SHP2-depleted pellet cultures." (PMID 24875294, 2014). "These activities of FGF21 and possibly FGF19 on adipocytes that elicit tumor suppressive metabolic signals appear sufficient to override tumor-promoting effects of elevated bile acids, inflammation and mild metabolic abnormalities elicited by the FGFR4 deficiency." (PMID 24279986, 2013). "Interestingly, while minimal positive staining was observed in PNTAT, FGF21 was generally expressed in tumor tissues regardless of the molecular type." (PMID 38238320, 2024). "Although high FGF expression may drive the oncogenic FGF-FGFR axis and activate signaling that controls tumor cell growth and survival, FGF21 does not appear to stimulate cell proliferation despite the potential activation of mitogen-activated protein kinase (MAPK) signaling." (PMID 39211324, 2024). "Therefore, these canonical effects of FGF21 may not be directly relevant to the role of FGF21 in human cancer, and there has been no study describing the specific role of FGF21 in tumor cells." (PMID 31408968, 2019). "Therefore, FGF21 is thought not to be involved in the tumor-suppressing effects of the KF." (PMID 29443873, 2018). "Recent studies have indicated specificity of FGF21 for FGFR1-KLB in adipose tissue, and that the administration of rFGF21 to obese and diabetic patients does not stimulate tumor growth." (PMID 31408968, 2019).
cancer (61 papers, 2013 to 2026). A tumor composed of atypical neoplastic, often pleomorphic cells that invade other tissues. "Studies have also shown that the upregulation of FGF21 is linked to the progression of various cancers, including breast cancer." (PMID 41262444, 2025). "Given that Gdf15 and Fgf21 are both implicated in physiological outcomes associated with cancer treatment, these results provide an important foundational understanding of the biological pathways that initiate their expression." (PMID 39798881, 2025). "Here, we will discuss current studies and gaps in aberrant expressions and the underlying mechanisms of hepatic FGF21 observed in inter-organ crosstalk and cancer progressions." (PMID 36263162, 2022). "Other studies focused on the role of FGF21 as the major mediator of the association between low cancer risk and a vegan diet, via downregulation of serum IGF-1 levels." (PMID 31408968, 2019). "Several studies provided experimental evidence that circulating FGF-21 is implicated in cancer pathogenesis." (PMID 30425347, 2018). "At the molecular level, elevated plasma Fgf21 levels were associated with dysregulated metabolic and cancer-related pathways." (PMID 27470139, 2016). "However, the effects of endocrine FGF21 in cancers, as well as the underlying molecular mechanisms, remain largely unknown." (PMID 38238320, 2024). "Recent evidence indicates that myokine expression in cancer survivors displays complex, context-dependent patterns, with FGF21 and musclin exerting nuanced effects on metabolic adaptation and muscle preservation." (PMID 41303335, 2025). "Fibroblast Growth Factor 21 (FGF21), known for its anti-inflammatory and metabolic regulatory properties, is increasingly recognized for its potential role in cancer." (PMID 41426308, 2025). "The results of this study also indicated that cancer cells secreting high levels of FGF21 were resistant to anti-PD-1 monotherapy, whereas the combination of anti-FGF21 and anti-PD-1 therapies showed significant anti-cancer effects." (PMID 40242310, 2025). "FGF21, a stress-inducible myokine involved in mitochondrial protection and lipid oxidation, appears dynamically regulated in cancer survivors, with exercise interventions significantly attenuating its proinflammatory overexpression." (PMID 41303335, 2025). "Both metabolic dysfunction and cancer are characterized by changes in circulating factors, such as fibroblast growth factor 21 (FGF21), growth differentiating factor 15 (GDF‐15), leptin and inflammatory cytokines." (PMID 40237521, 2025). "The close relationship between the liver and FGF21 has provided a deeper understanding of the FGF21-HCC axis compared to other cancers." (PMID 39211324, 2024). "The significance of FGF21 in oncogenesis has recently been highlighted; high levels of FGF21 have been observed in a variety of cancers, indicating its potential as a biomarker for cancer diagnosis and treatment." (PMID 39211324, 2024). "Regarding the expression of FGF21 in cancers, it is important to note that while increased serum FGF21 has been widely observed in various cancers, intratumoral FGF21 expression profiles are poorly understood." (PMID 38238320, 2024). "Given that cancer cells are resistant to apoptosis, we conducted further experiments to confirm the anti-apoptotic effects of FGF21." (PMID 38238320, 2024). "As a potential biomarker, the aberrant expression of FGF21 has been generally observed in different types and stages of cancers, which indicates its low specificity." (PMID 36263162, 2022). "Future studies regarding the role of aberrant pathological levels of FGF21 in cancer progression are therefore recommended." (PMID 36263162, 2022). "Overall, overexpression of FGF21 in both circulating and tissue levels has been found in different types and clinical stages of cancers, suggesting the biomarker value of FGF21 in cancer diagnosis and treatment." (PMID 36263162, 2022).